FOXP3 (forkhead box P3)
Diseases named in the same sentence as FOXP3 in open-access papers (continued):
Sharing a sentence is not in itself a finding about the gene and the disease.
panic disorder (1 paper, 2016). An anxiety disorder characterized by multiple unexpected panic attacks with persistent concern of recurring attacks. "It was hypothesized that panic disorder would be associated with impaired thymus function as reflected by reduced TRECs as well as by FOXP3 hypermethylation resulting in reduced immunosuppressive Treg function and accompanied by lower relative telomere length." (PMID 27362416, 2016). "In summary, the present study noted reduced TRECs in panic disorder patients compared to controls as well as FOXP3 hypermethylation in patients with panic disorder potentially reflecting impaired thymus and immunosuppressive Treg function." (PMID 27362416, 2016). "The present study demonstrated significant lower TRECs in both female and male panic disorder patients as well as significant hypermethylation of the FOXP3 promoter region in female patients with panic disorder as compared to healthy controls." (PMID 27362416, 2016). "Regression analysis (R2 = 0.059; p = 0.060) revealed that having panic disorder was an independent factor for higher FOXP3 methylation across all five CpGs (p = 0.020) in female patients." (PMID 27362416, 2016). "Differences in the methylation of FOXP3 promotor are quite small just above the background noise of the method and may be unable to explain all alterations found in patients with panic disorder." (PMID 27362416, 2016). "Likewise, FOXP3 demethylation could constitute a molecular correlate of beneficial effects of antidepressants on the immune system in panic disorder." (PMID 27362416, 2016). "Significantly lower TRECs (p = 0.004) as well as significant hypermethylation of the FOXP3 promoter region (p = 0.005) were observed in female (but not in male) patients with panic disorder as compared to healthy controls." (PMID 27362416, 2016). "Our study revealed hypermethylation of the FOXP3 promotor region—potentially resulting in reduced immunosuppressive Treg function—in female but not in male patients with panic disorders, corroborates the idea of a prematurely aged immune system in this particular patient subgroup." (PMID 27362416, 2016).
paracoccidioidomycosis (1 paper, 2015). A systemic fungal infection caused by Paracoccidioides brasiliensis that is most often seen in immunocompromised patients. "In human paracoccidioidomycosis (PCM), a study has shown an augmented number of CD4+CD25+Foxp3+ T cells in the lesions and in the peripheral blood of infected patients, and these cells exhibited strong suppressive activity." (PMID 26512987, 2015).
pediatric cancer (1 paper, 2015). "High expression of FOXP3, CD14, and ARG1 mRNA in the primary tumors of high-risk NB patients was predictive of better survival, suggesting that the immune status of the tumor may influence the natural history of this pediatric cancer." (PMID 26161395, 2015).
pemphigus foliaceus (1 paper, 2020). Pemphigus foliaceous is a rare superficial pemphigus disease characterized by multiple, pruritic, scaly, crusted cutaneous erosions, with flaky circumscribed patches, localized mostly on the face, scalp, trunk and extremities, often presenting an erythematous base. "Does the variation of the forkhead box P3 gene FOXP3 haveany impact on pemphigus foliaceus?" (PMID 32639508, 2020).
Peri-Implantitis (1 paper, 2024). An inflammatory process with loss of supporting bone in the tissues surrounding functioning DENTAL IMPLANTS. "Meanwhile, the levels of RORγT and FOXP3 transcription factors, which are associated with FOXP3+/RORγT+ phenotype cells, can predict the progression of peri-implantitis." (PMID 39555067, 2024).
peripheral T-cell lymphomas (1 paper, 2024). "The role of FoxP3+ regulatory T cells (Tregs) in the tumour microenvironment (TME) of peripheral T-cell lymphomas (PTCLs) is complex, and their impact on overall survival (OS) is unclear." (PMID 39682197, 2024). "The role of FoxP3+ cells in the TME of peripheral T-cell lymphomas (PTCL) is complex." (PMID 39682197, 2024). "The role of FoxP3+ Tregs in the TME of peripheral T-cell lymphomas (PTCLs) is complex, and their impact on overall survival (OS) remains unclear." (PMID 39682197, 2024).
pneumococcal pneumonia (1 paper, 2012). A febrile disease caused by STREPTOCOCCUS PNEUMONIAE. "Immunohistochemistry and flow cytometry reveal higher levels of TGF-β protein in BALB/c lungs during pneumococcal pneumonia that correlates with a rapid rise in lung Foxp3+Helios+ T regulatory cells." (PMID 22563306, 2012).
polyposis (1 paper, 2020). "The specific ablation of RORγt gene in Foxp3+ T cells improved the polyp-specific immune surveillance and attenuated the polyposis, indicating the inflammatory activity of these cells." (PMID 32674255, 2020).
pouchitis (1 paper, 2012). Acute inflammation in the intestinal mucosa of the continent ileal reservoir (or pouch) in patients who have undergone ileostomy and restorative proctocolectomy (proctocolectomy, restorative). "Additionally, the probiotic VSL#3 increases the number of Foxp3+ Treg in the lamina propria of ileal pouches in patients with pouchitis." (PMID 22849659, 2012).
primary progressive multiple sclerosis (1 paper, 2024). A multiple sclerosis that is characterized by steady worsening of neurologic functioning, without any distinct relapses or periods of remission. "The objective of this study was to investigate regulatory T cells (Tregs) and monocytes; specifically, the expression of CTLA-4 (CD152) and FOXP3+ in CD4+CD25+ Tregs and the expression of CD40+ and CD192+ monocyte subpopulations in subjects with primary progressive multiple sclerosis (PPMS)." (PMID 38398067, 2024).
proctitis (1 paper, 2018). An inflammatory process affecting the anus. "We found that in UC patients with proctitis and left-sided colitis the proportion of LP CD3+CD4+Foxp3+ Tregs was significantly higher in inflamed tissue than uninvolved tissue." (PMID 30425718, 2018).
Psoriasiform dermatitis (1 paper, 2023). A skin abnormality characterized by redness and irritation, with thick, red skin that displays flaky, silver-white patches (scales). "Moreover, the vitamin D analog, Maxacalcitol, significantly inhibits IMQ-induced psoriasiform dermatitis and reduces IL-17A mRNA expression in the skin, while also increasing Foxp3+ Treg cells." (PMID 37818377, 2023).
psychological distress (1 paper, 2024). "This study examined associations between symptoms of maternal prenatal psychological distress and percentages of maternal circulating FoxP3+ Tregs and six Treg subpopulations expressing Helios, CD45RA, CTLA-4, PD-1, TIGIT, or TIM-3." (PMID 38016492, 2024).
pulpitis (1 paper, 2021). Inflammation of the dental pulp. "Several transcription factors have been identified to be involved in the TF-gene regulatory network of pulpitis, including GATA2, ETS1, FOXP3, STAT1, FOS, and JUN." (PMID 33777260, 2021). "Six transcription factors (i.e., GATA2, ETS1, FOXP3, STAT1, FOS, and JUN) were identified to play pivotal roles in pulpitis." (PMID 33777260, 2021).
rash (1 paper, 2023). "Within HIV negative DRESS patients, there was a positive correlation between dermal CD4+FoxP3+ T-cells with days from symptoms onset to sampling (p = 0.02), eosinophils count (p = 0.006), and BSA skin rash (p = 0.01)." (PMID 37215719, 2023). "Treg studies from SCAR are limited but increases in circulating and dermal skin infiltrating FoxP3+ Tregs in the acute phase of DRESS has been reported, with a positive correlation between dermal Treg numbers with days from rash onset found in one study." (PMID 37215719, 2023).
respiratory syncytial virus infection (1 paper, 2017). "H3K4 methyltransferase Smyd3 has been shown to target Foxp3 promoter region to increase its expression, promote iTreg cell development and protect mice from exacerbated inflammation during respiratory syncytial virus infection by a TGF-β-Smad3-dependent mechanism." (PMID 28598443, 2017).
retinal (1 paper, 2021). "Importantly, we also demonstrated that the increased recruitment of Foxp3+Tregs in the retina correlated with dampened retinal inflammation and improved b-wave amplitudes in the I/R injury model." (PMID 34831229, 2021).
retinal vasculitis (1 paper, 2020). Inflammation of the retinal vasculature with various causes including infectious disease; lupus erythematosus, systemic; multiple sclerosis; behcet syndrome; and chorioretinitis. "Further experiments using FoxP3+CD25hiCD4+ Treg isolated from > P50 3A9 mice (naïve) or from > P50 dTg (AgX), showed that 3A9 Treg were ineffective while AgX Treg, not only halted disease progression but reversed the pathological changes (retinal vasculitis) in some cases." (PMID 33013877, 2020).
salivary gland cancer (1 paper, 2023). A primary or metastatic malignant neoplasm that affects the major or minor salivary glands. "A selected number of immunohistochemical markers related to TILs (CD3, CD4, CD68, and FOXP3) and TAMs (CD68 and CD163) were investigated on major salivary gland cancers." (PMID 37465638, 2023).
Sch (1 paper, 2022). "In NF2 patients, the number of Foxp3-positive cells in Sch with a progressive course was significantly higher than in those without a progressive course, suggesting that growth may be associated with Foxp3-positive Tregs." (PMID 35628268, 2022).
schizophrenia (1 paper, 2022). A major psychotic disorder characterized by abnormalities in the perception or expression of reality. "In the present study, we investigated the association of FOXP3 gene polymorphisms and schizophrenia for the first time." (PMID 35641708, 2022). "This study investigated FOXP3 gene polymorphisms (rs3761548, rs3761549, and rs2232365) in Egyptian patients with schizophrenia." (PMID 35641708, 2022). "Consequently, in the current study, we focused on three FOXP3 gene single-nucleotide polymorphisms (SNPs): rs3761548 C/A, rs3761549 C/T, and rs2232365 A/G and their potential association with schizophrenia." (PMID 35641708, 2022). "We can consider this study as a light for the role of FOXP3 gene polymorphisms in schizophrenia." (PMID 35641708, 2022). "Second, the functions of FOXP3 and Treg cells in schizophrenia are still unclear and need more researches." (PMID 35641708, 2022). "Deletion of FOXP3 leads to loss of Treg cell anti-inflammatory functions and its conversion to proinflammatory cells, but this action is still not proved in schizophrenia." (PMID 35641708, 2022). "There are no previous studies about the association of FOXP3 gene polymorphisms with schizophrenia." (PMID 35641708, 2022).
sclerosing cholangitis (1 paper, 2024). A chronic, autoimmune inflammatory liver disorder characterized by narrowing and scarring of the lumen of the bile ducts. "Mechanistically, sclerosing cholangitis causes an altered intestinal microbiota composition, which promotes Foxp3+ Treg-cell expansion, and thereby protects against IBD." (PMID 38839272, 2024). "In addition, we identified an increased infiltration of Foxp3+ Treg cells in the inflamed colon of mice with concomitant sclerosing cholangitis in our mouse models." (PMID 38839272, 2024). "Accordingly, sclerosing cholangitis promotes IBD in the absence of Foxp3+ Treg cells." (PMID 38839272, 2024).
secondary progressive multiple sclerosis (1 paper, 2021). A multiple sclerosis with a clinical course characterized by a progressive accumulation of neurological disability, independent of relapses, following an initial relapsing-remitting (RR) phase. "In line, we could not find any Foxp3+ cells in ectopic follicles in the CNS of secondary progressive multiple sclerosis patients." (PMID 35069572, 2021).
seminoma (1 paper, 2024). A radiosensitive malignant germ cell tumor found in the testis (especially undescended), and extragonadal sites (anterior mediastinum and pineal gland). "Flow cytometry showed a statistically significant abundance of CD25 + FOXP3+ Treg cells in TGCT samples, with the highest percentage (0.10–2.89%, median of 1.31%) in seminoma “Tumor” areas." (PMID 38649788, 2024). "Despite sample heterogeneity, flow cytometric analysis revealed a significant increase of CD25 + FOXP3+ Treg cells in seminoma, compared to non-neoplastic testicular tissue, suggesting an important role in TGCT development." (PMID 38649788, 2024). "Importantly, a high density of cells expressing Treg-specific markers CD25 and FOXP3, or Tfh-specific markers CXCR5 and BCL6, were found mainly in seminoma." (PMID 38649788, 2024).
shigellosis (1 paper, 2012). Shigellosis is a bacterial infection leading to dysentery and is caused by Shigella, which are small, ubiquitous Gram-negative bacteria belonging to the enterobacteria family. "Infiltration of the surface epithelium and lamina propria by γδ+ CD4+ and CD8+ T-cells occurs in human shigellosis with CD3+CD4+FoxP3+ T regulatory (Treg) cells maintaining gut tolerance by suppressing local antigen specific immune responses to commensal bacteria." (PMID 22887873, 2012).
Sm (1 paper, 2018). "IL-4Rα expression by Foxp3+ Treg cells was further enhanced following Sm infection, suggesting a strong requirement for this receptor either to preserve Treg cell activity or foster their transdifferentiation into ex-Foxp3 Th2 cells." (PMID 30379806, 2018). "CD4+ Foxp3+ Treg cells expressed IL-4Rα under a steady state and up-regulated their expression upon Sm infection." (PMID 30379806, 2018).
small cell carcinoma (1 paper, 2024). A neuroendocrine carcinoma composed of small malignant cells which are often said to resemble "oat cells" under the microscope. "Overexpression of FOXP3Δ3 or FOXP3 in PARCB1 lines led to minimal induction of PD-L1 expression, suggesting additional factors perhaps required in small-cell cancers that may be critical in expression of PD-L1." (PMID 39099201, 2024).
somatotrophinomas (1 paper, 2020). "Within NF-PitNETs, increased amounts of infiltrating CD4+ and FOXP3+ T cells were associated with bigger vessels, while in somatotrophinomas larger vessels correlated with more macrophages." (PMID 32946040, 2020).
spinal chordoma (1 paper, 2020). A slow-growing malignant bone tumor arising from the remnants of the notochord and occurring in the spine. "We reported that the IRS composed of tumoral PD‐1+ and Foxp3+ TILs as well as stromal CD8+ and Foxp3+ TILs was significantly correlated with the survival of spinal chordoma patients." (PMID 32508056, 2020).
synovial sarcoma (1 paper, 2024). "In synovial sarcoma, patients with higher CD8+ or FOXP3+ lymphocyte infiltration were associated with good overall survival, whereas patients with higher CD163+ macrophage infiltration had significantly lower overall and progression-free survival." (PMID 38240704, 2024).
Thromboembolism (1 paper, 2022). The formation of a blood clot inside a blood vessel that subsequently travels through the blood stream from the site where it formed to another location in the body, generally leading to vascular occlusion at the distant site. "According to the results of estimated marginal means (estimates of the probability of the particular allele), for SNP FOXP3 rs3761548, the TT (AA) genotype in the group of the patients with thromboembolism has a significant probability of presence (p value = 0.0439)." (PMID 36362759, 2022).
thrombophilia (1 paper, 2024). A condition characterized by an abnormally high level of thrombi. "For instance, IL-10 polymorphism, RAAS, FOXP3, thrombophilia, and NOS3 were found to be associated with an increased risk of PE." (PMID 39194706, 2024).
thymic lymphoma (1 paper, 2013). "Conditional deletion of Fbxw7 in CD4+ cells, or deletion of Nr4a3 and the closely related Nr4a1, resulted in hyper-proliferation of T cells, thymic lymphoma's and lethal lymphoproliferation, a phenotype similar to Foxp3−/− mice." (PMID 23825948, 2013).
tick-borne encephalitis (1 paper, 2024). Tick-borne encephalitis is caused by an arbovirus of the Flaviviridae family (tick-borne encephalitis virus, TBEV), transmitted principally by the bite of the Ixodes ricinus tick. "An evaluation of Foxp3+ Tregs during the tick-borne encephalitis (TBE)-induced response showed that high responders had decreased Tregs." (PMID 39340024, 2024).
toxoplasmosis (1 paper, 2015). A parasitic disease contracted by the ingestion or fetal transmission of toxoplasma gondii. "Notably, FoxP3- T-bet+ Th1 cells are thought to be the critical source of IL-10 during toxoplasmosis, but since previous studies have shown that the AHR is not expressed at detectable levels in Th1 cells it was unlikely that AHR activity would directly affect IL-10 production by this population." (PMID 26010337, 2015).
transient ischemic attack (1 paper, 2015). A brief attack (from a few minutes to an hour) of cerebral dysfunction of vascular origin, with no persistent neurological deficit. "Predictors of fraction of FoxP3 Treg in patients with acute ischemic stroke/transient ischemic attack (multivariate analysis)." (PMID 26512654, 2015). "Predictors of the absolute number or fraction of immune cells in patients with acute ischemic stroke/transient ischemic attack (univariate analysis; (CD4+CD8− T cells, CD8+CD4− T cells, FoxP3 Treg)." (PMID 26512654, 2015).
Trematode Infections (1 paper, 2013). Infections caused by infestation with worms of the class Trematoda. "In summary, alongside its role in controlling CD4+ Teff-cell responses, ICOS co-stimulation promotes the expansion and maintenance of Foxp3+ Treg cells in both nematode and trematode infections." (PMID 23319295, 2013). "Thus, upregulation of ICOS by Foxp3+ Treg cells is a common feature of both nematode and trematode infections." (PMID 23319295, 2013).
ulcerative stomatitis (1 paper, 2020). Inflammation of the mouth mucosa associated with the presence of ulcers. "The current study confirms the presence of moderate to large numbers of FoxP3+ T cells and IL17+ cells in all ulcerative stomatitis lesions using confocal immunofluorescence." (PMID 31923271, 2020).
undifferentiated pleomorphic sarcoma (1 paper, 2021). An undifferentiated soft tissue sarcoma characterized by the presence of a pleomorphic malignant cellular infiltrate. "Also, PD-L1 expression, FOXP3+ Tregs infiltration and PD-L1/FOXP3 were significantly associated with overall survival in patients with undifferentiated pleomorphic sarcoma." (PMID 34440139, 2021).
urinary tract infection (1 paper, 2021). "CD4+Tbet+IFN-γ+ and CD4+FoxP3+IL-10+ T cell populations were decreased in HbSS subjects with asymptomatic urinary tract infections." (PMID 34239376, 2021).
urothelial carcinoma (1 paper, 2016). A malignant neoplasm derived from the transitional epithelium of the urinary tract (urinary bladder, ureter, urethra, or renal pelvis). "Except for the gender factor, there was lack of any association between Foxp3 expression and other clinicopathological factors, including age, history of urothelial carcinoma, and tumor number, morphology, grade, and pathological stage (all p values > 0.05)." (PMID 27557492, 2016).
uterine serous carcinomas (1 paper, 2023). "This trend was not as prominent for CD8+, FOXP3+, or CD68+ immune cells in this cohort of uterine serous carcinomas." (PMID 36672477, 2023).
vitamin A deficiency (1 paper, 2012). Deficiency of vitamin A due to malnutrition, malabsorption, or dietary lack. "Further studies are needed to determine the mechanism of expansion and suppressive function of Foxp3+ Tregs induced during vitamin A deficiency." (PMID 22927819, 2012).